TRAF6 (TNF receptor associated factor 6)
Diseases named in the same sentence as TRAF6 in open-access papers (continued):
Sharing a sentence is not in itself a finding about the gene and the disease.
cancer (continued). "In addition, the link between TRAF6 and autophagy also results in cancer progression." (PMID 36202787, 2022). "However, whether cancer patients with high TRAF6 expression are more sensitive to PD-1/PD-L1 blockade requires further investigation." (PMID 35361799, 2022). "In addition, TRAF6 was reported to promote cell proliferation and migration in many cancers." (PMID 36237831, 2022). "Besides that, TRAF6 inhibition was shown to inhibit cancer cachexia." (PMID 34572540, 2021). "Phosphoproteomic experiments show that TRAF6 and its phosphorylation contribute to the remodeling of LPS- and autophagyinduced signaling networks, revealing an intricate link between inflammatory and metabolic processes that are frequently dysregulated in cancer." (PMID 34298830, 2021). "Having shown that p62 negatively regulates Toll-like receptor 4 (TLR4)-mediated signaling via TRAF6-ECSIT signaling axis, we herein investigated whether p62 is functionally implicated in the TRAF6-BECN1 signaling axis, thereby regulating cancer cell migration and invasion." (PMID 32384667, 2020). "In short, TRAF6 may represent a new cancer prognostic biomarker or potential therapeutic target." (PMID 33294443, 2020). "Thus, most evidence indicates that TRAF6 is an oncogene in human cancers." (PMID 30294322, 2018). "IL-6 and IL-8 can further activate STAT3, which has been shown to promote apoptotic resistance and contribute to poor prognosis of cancer patients Although TRAF6 is known to mediate LPA-stimulated NF-κB activation, it is not clear whether TRAF6 plays a particular role in the LPA2 receptor signaling." (PMID 27134758, 2016). "This is an important cytokine that plays a role in cancer, with two protein families implicated in the signaling mediated by the TNF receptor: 1) death-domain proteins, such as TRADD, FADD, TNFR1, RIP; and 2) TRAF domain-containing proteins, such as TNFR2, CD40, TRAF1, TRAF6." (PMID 26143641, 2015). "Experiments using either xenograft or genetic mouse models illustrated that deficiency in Skp2, TRAF6 or TRAF4 results in suppression of cancer development in vivo, pointing to the critical role of distinct E3 ubiquitin ligases in Akt-mediated biological functions and cancer progression." (PMID 25309720, 2014). "TRAF6 activates TLR2/4 via autophagic flux to release SIRT2 into the extracellular space (eSIRT2), which facilitates cancer cell metastasis and invasion." (PMID 40727252, 2025). "Seventy-four unique Reactome terms were selected in IStoI comparison, including “MAP2K and MAPK activation”, “TRAF6-mediated IRF7 activation”, “CTLA4-inhibitory signaling”, “signaling by Hippo” and “signaling by WNT in cancer”." (PMID 39000404, 2024). "This analysis revealed that TRAF1, TRAF2, TRAF3, TRAF4, TRAF6, and TRAF7 exhibit higher expression levels in cancer tissues, whereas TRAF5 is expressed at lower levels in these tissues." (PMID 38825674, 2024). "Previous studies have demonstrated that TRAF6 activates the AKT pathway, promoting PCa advancement and invasion both in vitro and in vivo, highlighting its significant contribution to cancer progression 118-120." (PMID 38169510, 2024). "The analysis of 33 cancer types revealed that TRAF2, TRAF3, TRAF4, and TRAF7 are predominantly overexpressed, whereas TRAF1, TRAF5, and TRAF6 exhibit lower expression levels." (PMID 38825674, 2024). "In one study, using a cinchonine drug capable of targeting the TRAF6 molecule, ubiquitination reduced AKT while inhibiting TAK1 activity and promoting apoptosis in cancer cells." (PMID 37443080, 2023). "Compared with normal tissues, CCL3 was highly expressed in cancer tissues, while CCR5, NF-κB, TRAF6, and PI3K were highly expressed in cancer tissues and metastatic lymph nodes." (PMID 35935327, 2022). "USP1 function as an oncogene by interacting with DNA repair signal through PCNA and FANCD2, USP4 promote cancer progression by deubiquitinating TRAF2 and TRAF6 and thereby regulating the TGFβ signaling pathway." (PMID 34545063, 2021).
cancer (continued). "Given the importance of CCL3 and CCR5 in cancer progression, we tested the impression of BFT-1 on the expression of CCR-5/CCL3, TRAF6/NF-κB." (PMID 33981848, 2021). "Studies have shown that the TRAF6-induced ubiquitination of BECN1 plays a key role in TLR-induced autophagy activation, thereby functionally implicating cancer progression and migration." (PMID 32384667, 2020). "The cancer stem-like cell marker Lgr5 and differentiation marker CK18 were detected using RT-PCR in HGC-27 and MGC-803 cells; TRAF6 knockdown resulted in the downregulation of Lgr5 and upregulation of CK18." (PMID 32724313, 2020). "Among the identified genes, TRAF6 was identified as a gene of interest, as previous studies showed that TRAF6 regulates the activation of NF‐κB signalling and affects NF‐κB‐mediated EMT in carcinogenesis and cancer development." (PMID 32436333, 2020). "It has been demonstrated that microRNA-146a can target many genes, such as IRAK1, IRAK2, TRAF6, RIG-I, IRF-5, STAT-1, PTC1, Numb, and WASF2, to play a variety of roles in human diseases, including cancers and inflammatory immune diseases." (PMID 31798643, 2019). "TRAF6 belongs to the TRAF family 18, 19, which has been reported to promote cancer tumorigenesis, invasion and metastasis 22, 23, 48, and participate in a variety of signal pathways." (PMID 29193723, 2018). "Stimulation with IFN-γ, TLR ligands and LPS via MyD88, TRAF6, MEK, STAT1, NF-κB and PI3K-dependent pathways increased PD-L1 expression in different types of cells, such as inflammatory cells, fibroblasts and cancer cells." (PMID 29690901, 2018). "NF‐κB signalling plays a crucial role in cancer stem cell biology 42, and TNF‐α‐induced NF‐κB activation elevated CD44 expression in SCCHN cells, but TRAF6 knockdown markedly attenuated this process." (PMID 29193723, 2018). "USP4 has previously been confirmed to target TRAF2 and TRAF6 for deubiquitination and it has been established that USP4 inhibits TNFα-induced cancer cell migration." (PMID 30194441, 2018). "Amplification of TRAF6 was identified in lung cancer, which serves to activate NF-κB pathway in RAS-driven cancer." (PMID 26769849, 2016). "Within the down-regulated signaling pathways, there were ubiquitin-mediated proteolysis, mTOR signaling, pathways in cancer, RIG-like receptor signaling pathway with Herc1 and Traf6, Mapk1 and Rps6ka3, Ifg1r, Prkx, and Foxo1 as the core regulatory factors." (PMID 26900402, 2016). "Downstream IRAK1 signaling was suppressed through TRAF6, attenuating activation of NF-κB and MAPK and stimulating cancer cell death, thus highlighting the potential use of IRAK1 inhibitors in the treatment of HNSCC." (PMID 26527316, 2015). "We also found that TRAF6 stabilized MCL-1 in mouse fibroblasts and in several cancer cell lines including HeLa and MCF-7." (PMID 25340740, 2014). "It has been recently shown that TLR9 stimulation with agonistic CpG sequences stimulates invasion in various cancer cells via MYD88-independent and TRAF6 partially dependent pathways." (PMID 24459426, 2013). "In sum, our study uncovers a novel cell cycle control mechanism by ZDHHC17-mediated palmitoylation and TRAF6-mediated ubiquitination of CDK4, presenting a potential therapeutic avenue by targeting the ZDHHC17-TRAF6-CDK4 axis for cell cycle dysregulated cancers." (PMID 42133178, 2026). "Given that USP11 is functionally linked to TLR-mediated signaling through the stabilization of TRAF6, we explored whether TLR activation influences cancer progression in USP11-KO CRC cells." (PMID 41419456, 2025).
cancer (continued). "Studies have shown that TRAF6 induces ubiquitination of ULK1 by Lys63 chain, which stabilizes the expression of autophagy protein ULK1 and promotes the occurrence of autophagy, thereby promoting the progression of malignant tumors." (PMID 38135696, 2024). "Notably, within the context of ESCC, it has been observed that cancer cells induce elevated levels of miR-146a in peripheral blood mononuclear cells (PBMCs), resulting in the downregulation of IRAK1 and TRAF6." (PMID 38169510, 2024). "Hence, small compounds targeting the concerned E3 ligases such as SCFβ‐TrCP, TRAF6, LUBAC and IAPs have been developed for cancer treatment." (PMID 36881608, 2023). "In addition, TRAF6 is closely related to EMT pathway and cancer cell stemness, which mediate migration and invasion of HNSCC cells." (PMID 35096063, 2022). "In keeping with the notion that TRAF6 positively regulated PD-L1 stability, depletion of endogenous TRAF6 using sgRNAs markedly decreased the PD-L1 protein level, but did not significantly affect the PD-L1 mRNA level in multiple cancer cell lines." (PMID 35361799, 2022). "Apart from targeting Skp2, development of specific inhibitors targeting Akt upstream regulators, such as TRAF6, SETDB1 and JMJD2A, may also serve as a novel and innovative strategy for eradicating hyperactive Akt-driven human cancers." (PMID 36180910, 2022). "Furthermore, TRAF6 is needed for the activation of AKT kinase, which is involved in cancer progression." (PMID 33430277, 2021). "Our previous study has found that YPFS could regulate p62/TRAF6 signaling, WT1/MVP axis and mTORC2/AKT signaling, which account the anti-MDR effects and anti-cancer effects both in vivo and in vitro models." (PMID 34135758, 2021). "TRAF6 E3 ligase promotes activation of PI3K pathway in cancer by nonproteolytic polyubiquitination of PI3K catalytic subunit p110α." (PMID 33004065, 2020). "Additionally, CRBN inhibited TRAF6-induced ubiquitination of BECN1 (Beclin 1), and that induced autophagy activation in CRBNKD THP-1, CRBN-knockout (CRBNKO) H1299, and CRBNKO MCF7 cancer cells in response to TLR4 stimulation." (PMID 31620128, 2019). "Based on these results, we speculated that TRAF6 may play a role in SCCHN progression, especially in metastasis, which is a characteristic of cancer stem cells." (PMID 29193723, 2018). "TRAF4 and TRAF6 are also involved in the signaling of TGF-β receptor, triggered by TGF-β, which, if dysregulated can lead to induction of apoptosis, epithelial–mesenchymal transition, and cancer cell invasion." (PMID 30428531, 2018). "In general, TRAF6 may participate in the cell growth and apoptosis in HCC as well as other cancers being reported." (PMID 27708550, 2016). "The protein levels of TRAF2 and TRAF6 were reduced in cancer cell lines treated with NA, but not TRAF3, TRADD, and FADD." (PMID 25575821, 2015). "The detailed molecular mechanisms by which TRAF6 deactivates the JAK-STAT pathway should be investigated further, as well as its biological roles in antiviral response, immune and inflammatory response and cancer." (PMID 23185365, 2012). "The residue K242 is also ubiquitinated by the E3 ubiquitin ligases TRAF6 and/or SKP2, suggesting that KDM5B protein levels may be differentially regulated by synchronization of the ubiquitination and sumoylation machinery in cancers." (PMID 36697763, 2023). "While TRAF6 exhibits similar levels in other cancer cell lines, the entire TRAF6 signaling pathway may not be in a state of hyper-activation." (PMID 37389738, 2023). "The present study therefore raises the possibility that a drug inhibiting the TRAF6 E3 ligase activity may also unleash the power of cytotoxic T cells to destroy cancer cells, without developing the serious adverse effects seen in TRAF6 KO mice." (PMID 35157702, 2022). "In addition, OSCC patients with expression of TRAF6 showed a trend towards poorer cancer-specific survival when compared with patients without TRAF6 expression." (PMID 29703234, 2018).
cancer (continued). "However, whether TRAF6 plays a critical role in the cross talk between UPS and autophagy in OSCC cancer cells remains undetermined." (PMID 29703234, 2018). "Subsequent both in vitro and in vivo experiments distinctly demonstrate that cinchonine could induce apoptosis and reduce proliferation of cancer cells; and that the mode of action is blocking the AKT and TAK1 activations though interfering the formation of the TRAF6-Ubc13 complex." (PMID 28231796, 2017). "TRAF6 and MCL-1 may therefore represent viable therapeutic targets for ATL and other cancers." (PMID 25340740, 2014). "Moreover, TRAF6 has been reported to enhance the ubiquitination and activation of protein kinase B (AKT) and transforming growth factor activated kinase 1 (TAK1), leading to cell cycle progression, proliferation, and migration of cancer cells along with impairment of apoptosis in cancer cells." (PMID 38004473, 2023). "Cinchonine, a member of the Cinchona alkaloid family, could complex with the RING domain of TRAF6, leading to the disruption of the binding with its natural ligand, the Ubc13 protein, thereby inhibiting the AKT and TAK1 signaling pathways and inducing the apoptosis of cancer cells." (PMID 33294443, 2020). "Over-expression of TRAF6 could increase phosphorylations of AKT at Thr-308 and Ser-473 as well as AKT ubiquitination, leading to enhanced AKT activity, and many reports suggest that the expression level of ubiquitination-AKT is higher in cancer cells than normal cells." (PMID 28231796, 2017). "Importantly, TRAF6 was found to be autoubiquitinated, which is consistent with its activation, during mitotic progression at the same time as AURKB is active, in agreement with our hypothesis that active TRAF6 has impact on AURKB to regulate proliferation of cancer cells." (PMID 35853811, 2022). "Therefore, TRAF6-mediated MCL-1 stabilization appears to be a common mechanism of cell survival usurped by both viral and non-viral cancers." (PMID 25340740, 2014). "Thus, TRAF6 regulates the basal stability of MCL-1 in some, but not all cancer cell lines." (PMID 25340740, 2014).
infection (134 papers, 2009 to 2025). The state of being infected such as from the introduction of a foreign agent such as serum, vaccine, antigenic substance or organism. "During the late stage of infection, CYLD re-associated with the TRAF6/sNASP complex to terminate infection-induced lung inflammation by inhibiting TRAF6 activation." (PMID 40108019, 2025). "As a fundamental bridge in various signaling pathways, TRAF6 is crucial to maintaining cellular homeostasis caused by pathogen infection." (PMID 38016969, 2023). "HSV US3 protein kinase inhibited NF-κB activation, which is required for the host immune response to infection by reducing TNF receptor-associated factor 6 (TRAF6) ubiquitination or hyperphosphorylation of the p65 protein." (PMID 36386680, 2022). "The miR-146a plays a role in regulating the expression of IL-1 receptor-associated kinase and TNF-receptor-associated factor 6 after LPS infection." (PMID 34067819, 2021). "Induction of miR-146a and miR-146b by infection was shown to be affected by deficiencies in Traf6 and Myd88, which are central intermediates of Toll-like receptor and cytokine signalling pathways." (PMID 24112639, 2013). "Additionally, BPLF1 deubiquitinates the TNF receptor-associated factor 6 (TRAF6), inhibiting NF-κB signaling during lytic infection." (PMID 34943147, 2021). "Furthermore, TRAF6 deficiency resulted in impaired activation of the IFNβ promoter in response to infection with encephalomyocarditis virus (EMCV), a positive-sense ssRNA virus recognized by MDA5." (PMID 19479062, 2009). "In the case of infection with the susceptible strains, besides the increased methylation level of Traf6 gene and hypomethylation of Irak-2 gene, normal methylation of the other tested genes related to the TLR signaling pathway was observed, which may induce effective responses to infection." (PMID 32605029, 2020). "This suggested dual regulatory roles of ECSIT, as evidenced by prior work: 1) maintaining basal autophagy homeostasis via Parkin-dependent mitophagy, and 2) mediating infection-induced autophagy through TRAF6 ubiquitination." (PMID 41209015, 2025). "MDMs were transfected with pooled siRNAs against TRAF6 or IKK-β prior to infection with LaiΔenvGFP/G or replication-competent HIV-1/Lai-YU2env." (PMID 40493408, 2025). "For instance, upon infection with oncolytic alphaviruses, proteins like RIG-I and TNF receptor-associated factor-6 (TRAF-6) are engaged, leading to the amplification of antiviral responses." (PMID 38731910, 2024). "The gene expression levels of TRAF6 rapidly increased after infection and reached a maximum of 48 hpi, with 2.41-fold increases compared to the control group." (PMID 39458388, 2024). "FK506-binding protein 51 (FKBP51) interacts with TRAF6 to promote the expression of type I interferon and inhibit the infection of Newcastle disease virus." (PMID 38995016, 2024). "TRAF6 is a key regulator of canonical NF-κB signaling, which plays an important role in the immune response against pathogen infection." (PMID 38241362, 2024). "Compared to the control, the level of TRAF6 expression decreased during infection of GI.1 (11.5-fold reduction (p = 0.002)), while during GI.2, it was only a 3.4-fold reduction (p = 0.017)." (PMID 39273479, 2024). "The significant drop in the expression levels of TRAF6 at later times of infection, specifically at 24, 48, and 72 hpi, strongly suggests the activation of inhibitory anti-inflammatory mechanisms driven by both anti-inflammatory miRNAs." (PMID 37376550, 2023). "The results indicate that ALV-A upregulates TRAF6 by inhibiting its ubiquitination at 72 h of infection." (PMID 36298765, 2022).